GPR162 (G protein-coupled receptor 162)
Description:
Orphan receptor.
Synonyms: GRCA; A-2
Tractability: Small molecule: it belongs to a druggable protein family. Antibody: UniProt places it where antibodies can reach, with medium confidence; UniProt predicts a signal peptide or a membrane-spanning region; its Gene Ontology location is reachable by antibodies, with medium confidence. PROTAC: its protein half-life has been measured.
Target class: Family A G protein-coupled receptor; Membrane receptor
Gene: Protein-coding gene on chromosome 12 (6,821,624 to 6,829,972, forward strand). Ensembl gene ENSG00000250510.
Subcellular location: Cell membrane
Subcellular location (Human Protein Atlas): Centriolar satellite
Gene Ontology:
Molecular function: protein binding; G protein-coupled receptor activity
Biological process: G protein-coupled receptor signaling pathway
Cellular component: membrane; plasma membrane
Genetic constraint (gnomAD): Loss-of-function variants: 26 observed, 44.75 expected, observed/expected ratio (o/e) 0.58, 90% interval 0.43 to 0.81. The upper end of that interval is the gene's LOEUF score, 0.81, which puts it in group 3 of 6, group 1 being the genes least tolerant of losing a copy. Missense variants: 704 observed, 811.52 expected, observed/expected ratio (o/e) 0.87, 90% interval 0.81 to 0.92. Synonymous variants: 362 observed, 341.03 expected, observed/expected ratio (o/e) 1.06, 90% interval 0.97 to 1.16.
Homologues: Orthologues: chimpanzee GPR162 (100% identical), macaque GPR162 (99% identical), pig GPR162 (97% identical), rabbit GPR162 (97% identical), dog GPR162 (96% identical), mouse Gpr162 (96% identical), rat Gpr162 (95% identical), guinea pig GPR162 (95% identical), tropical clawed frog gpr162 (53% identical). Paralogues in human: GPR153 (46% identical).
Diseases named in the same sentence as GPR162 in open-access papers:
GPR162 is named in the same sentence as 11 diseases in open-access papers, as found by Europe PMC text mining. Sharing a sentence is not in itself a finding about the gene and the disease. The quoted sentences say what the papers report.
lung carcinoma (2 papers, 2023 to 2024). "To identify the particular interaction sites of the two, we built locations with a high mutation frequency of GPR162 and STING in lung cancer." (PMID 36725837, 2023). "To reveal the physiological significance of GPR162 in lung cancer, we constructed cell lines stably overexpressing GPR162 in A549 and PC9 cells." (PMID 36725837, 2023). "Meanwhile, GPR162 protein and mRNA levels were measured in lung cancer cell lines and normal lung tissue cells, it was shown that the expression of GPR162 in normal cells was much higher than those in lung cancer cell lines." (PMID 36725837, 2023). "We discovered that the immunohistochemistry score of GPR162 in lung cancer and liver cancer tissues was lower than that of neighboring normal tissues when compared to normal tissues." (PMID 36725837, 2023). "The mRNA level of STING was detected in GPR162 overexpressed and knockdown liver and lung cancer cell lines, indicating that GPR162 may regulate STING via posttranslational modification rather than transcriptional regulation." (PMID 36725837, 2023). "Next, we stably knocked out GPR162 in the H358 cell line and knocked down GPR162 in the HBE cell line, also detecting the physiological effects of GPR162 depletion on lung cancer." (PMID 36725837, 2023). "Liu Shuang and colleagues investigated lncRNA-microRNA interactions, chromatin modifiers, and ferroptosis in lung cancer, as well as the oncogenic role of GINS4, the tumor-suppressive function of GPR162 in radiotherapy, the impact of AhR on NSCLC, and the targeting of USP8 in HCC treatment." (PMID 39944353, 2024).
breast carcinoma (1 paper, 2023). "Kaplan–Meier analysis evaluated the survival rate of patients with liver cancer, lung adenocarcinoma, and breast cancer, and found that patients with high GPR162 expression had a better prognosis." (PMID 36725837, 2023).
dementia (1 paper, 2024). Loss of intellectual abilities interfering with an individual's social and occupational functions. "Therefore, the decrease in GABRD+ or GPR162+ carrying pTau217 EVs may simply be due to neuronal loss as dementia progresses, although other mechanisms require further investigation." (PMID 38444036, 2024).
insulinoma (1 paper, 2025). "GPR162 is also present in human and murine pancreatic islets, and has been shown to regulate cocaine-amphetamine-regulated transcript (CART)-induced insulin secretion in a rat insulinoma cell line INS-1 832/13." (PMID 40544420, 2025).
lung adenocarcinoma (1 paper, 2023). A carcinoma that arises from the lung and is characterized by the presence of malignant glandular epithelial cells. "Here, we used the TCGA database to analyze the expression and survival curves of GPR162 in a variety of solid tumors, including lung adenocarcinoma, and found that the reduction of GPR162 led to more tumors and reduced survival rates." (PMID 36725837, 2023). "In addition, we detected the protein and mRNA levels of GPR162 in lung adenocarcinoma tissues and normal tissues adjacent to cancer and found that GPR162 was expressed higher in normal tissues." (PMID 36725837, 2023).
ovarian carcinoma (1 paper, 2021). A malignant neoplasm originating from the surface ovarian epithelium. "Among 86 genes linked to ovarian cancer in previous publications, our data contained expression values for 42, and of these, tests of LIME1, GPR162, STAB1, and SKAP1, resulted in unadjusted p<0.05." (PMID 34449791, 2021). "Among genes previously linked to ovarian cancer, tests of LIME1, GPR162, STAB1, and SKAP1 resulted in unadjusted p-values <0.05." (PMID 34449791, 2021).
tumor (7 papers, 2014 to 2025). "We also identified a loss-of-function variant in the GPR162 gene in our patient’s right corticotroph tumor." (PMID 40544420, 2025). "In summary, we report for the first time a double pituitary corticotroph tumor which harbored a G-protein coupled receptor (GPR162) variant in one tumor and a novel ubiquitin specific protease (USP8) variant in the second corticotroph tumor in the setting of a background germline CYP21A2 variant." (PMID 40544420, 2025). "Interestingly, we also identified a loss-of-function variant in the GPR162 gene in our patient’s right corticotroph tumor." (PMID 40386408, 2025). "The tumor volume of the control group was reduced by around 55% following radiotherapy, whereas the volume of the overexpression group was reduced by about 85%, implying that the overexpression GPR162 group was more susceptible to radiotherapy." (PMID 36725837, 2023). "WES demonstrated a loss-of-function variant in the G-protein coupled receptor 162 [GPR162 (R218*)] in the right corticotroph tumor, and a novel missense variant in ubiquitin specific peptidase 8 [USP8 (P681Q)] in the left tumor." (PMID 40544420, 2025). "Functional studies in murine corticotroph tumor cells demonstrated that GPR162 negatively regulates POMC mRNA expression and the GPR162 variant R218* that we had demonstrated in our index patient blunted the suppressive effect of WT GPR162." (PMID 40544420, 2025). "In conclusion, as a novel tumor inhibitor and radiotherapy sensitizer, GPR162 can promote the entry of DNA damage into the cytoplasm and activate the STING-IFN system to improve cancer radiotherapy." (PMID 36725837, 2023). "In consideration of these findings, it is extremely interesting how GPR162 activation on ISGs genes and related tumor immunity, which will be explored in our further studies." (PMID 36725837, 2023). "GPR162 deletion resulted in a considerable rise in tumor growth, volume, and weight, according to our findings." (PMID 36725837, 2023). "The injection of A549 cells overexpressing GPR162 can drastically Inhibit tumor growth, volume, and weight when compared to the injection of control cells, while the overall body weight of the mice remains unchanged." (PMID 36725837, 2023). "A xenograft model experiment was used to further investigate the influence of GPR162 on tumor development in vivo." (PMID 36725837, 2023). "In addition, GPR162, a novel tumor suppressor and radiosensitizer, effectively inhibits tumor progression by activating the STING-dependent DNA damage repair pathway." (PMID 40166469, 2025). "Functional studies in murine corticotroph tumor cells demonstrated that GPR162 negatively regulates P OMC mRNA expression and the GPR162 variant R218* that we had demonstrated in our index patient also resulted in reduced corticotroph tumor POMC mRNA expression." (PMID 40386408, 2025). "In conclusion, GPR162 can be used as a novel tumor suppressor to promote the activation of STING in the DNA damage response induced by radiotherapy, and then activate STING to induce DNA damage of tumor cells, thus inhibiting the occurrence and development of tumors." (PMID 36725837, 2023). "Furthermore, STING inhibitors can greatly reduce the anti-tumor impact of radiotherapy, implying that GPR162 increases the radiotherapy sensitivity of tumors by activating the STING signaling pathway." (PMID 36725837, 2023). "Finally, these findings show that GPR162 overexpression is associated with cell proliferation, colony formation, migration and invasion, and tumor development, as well as having a strong negative effect on tumor progression." (PMID 36725837, 2023). "Combined with in vitro experiments, We discovered that IR dramatically boosted GPR162 protein expression, indicating a potential role for this orphan type of GPCR in tumor irradiation." (PMID 36725837, 2023).
tumor (continued). "In contrast to its actions on POMC transcription, GPR162 overexpression did not alter corticotroph tumor cell proliferation or actions of Dexamethasone to suppress POMC transcription." (PMID 40386408, 2025). "Previous studies have confirmed that GPR162 can promote STING-related pathway-dependent DNA damage responses, thus we want to see if the GPR162-STING-DNA damage axis can be employed as a transformation strategy to boost the anti-tumor effect of radiation." (PMID 36725837, 2023).
cancer (3 papers, 2014 to 2023). A tumor composed of atypical neoplastic, often pleomorphic cells that invade other tissues. "To further investigate the significance of GPR162 in clinical, we examined GPR162 mRNA levels in a range of cancer patients from the TCGA database." (PMID 36725837, 2023). "Also, GPR162 has been shown to increase the radiation-induced DNA damage response and is involved in the activation of the type I interferon system in carcinoma cell lines." (PMID 38077141, 2023).
GPR162 also shares sentences with these, for which no sentence is quoted: diabetes (1 paper); Insulin resistance (1); liver cancer (1).